RPL22 (ribosomal protein L22)
Diseases named in the same sentence as RPL22 in open-access papers (continued):
Sharing a sentence is not in itself a finding about the gene and the disease.
anemia (1 paper, 2022). A reduction in the number of red blood cells, the amount of hemoglobin, and/or the volume of packed red blood cells.
atherosclerosis (1 paper, 2026). A disease characterized by the build-up of fatty material and calcium deposition in the arterial wall resulting in partial or complete occlusion of the arterial lumen. "LncAPAT promoted the macrophage inflammatory response and atherosclerotic plaque progression by inhibiting the transcriptional activity of RPL22, indicating its potential as a therapeutic target for atherosclerosis." (PMID 41527512, 2026).
bipolar disorder (1 paper, 2011). A disorder of the brain that causes unusual shifts in mood, energy, activity levels and the ability to carry out day-to-day tasks. "These genes included SBNO2, CEACAM5, AKAP1, UBC, ACTB, UBB, and FOS for schizophrenia; SEC24C, PGLYRP1, ARHGAP4, RPL22, SLC6A11, and SYK for bipolar disorder; and SRRT, PARK2, LILRA4, STK17A, IGFBP2, and NF1 for major depression." (PMID 22373040, 2011).
colon adenocarcinoma (1 paper, 2019). "Indeed, RPL22L1 expression was frequently elevated in colon adenocarcinomas relative to adjacent normal and normal colon tissue, whereas RPL22 was preferentially expressed in normal colon samples." (PMID 31581233, 2019). "Because RPL22 was found to be deleted frequently in CRC patients, we asked whether RPL22L1 expression was also elevated in primary human colon adenocarcinoma patient samples." (PMID 31581233, 2019).
diffuse gastric adenocarcinoma (1 paper, 2022). An adenocarcinoma arising from the stomach. "Interestingly, there was also a strong relation between them in diffuse gastric adenocarcinoma tissues (R = 0.409), implying that Drp1 and RPL22 might be a key signal cascade during the progression of gastric adenocarcinoma." (PMID 35230214, 2022).
endometrial tumors (1 paper, 2018). "Direct sequencing of RPL22 exons 2 and 4 in 226 MSI endometrial tumors confirmed 51.6% tumors were heterozygous for the 43delA mutation, which was also presented in RL95-2 cell line." (PMID 29416671, 2018).
esophageal cancer (1 paper, 2021). A primary or metastatic malignant neoplasm involving the esophagus. "In patients with stage IV esophageal cancer CYCS (p = 0.014), PON3 (p = 0.14), ACPP (p = 0.047), and RPL22 (p = 0.047) were significantly upregulated compared with patients with early-stage cancer." (PMID 33828156, 2021).
gastric intestinal type adenocarcinoma (1 paper, 2022). An adenocarcinoma of the stomach arising on a background of intestinal metaplasia. "Of note, in the subtypes of STAD including gastric mixed adenocarcinoma tissues (n = 171) and gastric intestinal-type adenocarcinoma tissues (n = 109) downloaded from the TCGA database, the association between Drp1 and RPL22 was stronger with the higher coefficient (R = 0.433 and R = 0.518)." (PMID 35230214, 2022).
inflammatory skin disease (1 paper, 2021). Inflammatory skin disorders covers a broad category that includes many conditions ranging in severity, from mild itching to grave medical health complications These disorders are common in people of all ages and races. "Therefore, this is the first study to report the differential expression and role of RPL22 in inflammatory skin diseases." (PMID 34220863, 2021).
osteosarcoma (1 paper, 2017). A usually aggressive malignant bone-forming mesenchymal neoplasm, predominantly affecting adolescents and young adults. "To determine if RPL22/eL22 could negatively affect cancer cell growth, we transfected osteosarcoma cell line U2OS with increasing amounts of the FLAG-L22 plasmid with an empty vector as a control, and counted the number of colonies after 10 days of selection with G418 treatment." (PMID 29207594, 2017).
periodontitis (1 paper, 2017). An acute or chronic inflammatory process that affects the tissues that surround and support the teeth. "A notable exception is RPL22 in experiments with Agac toxins (periodontitis), ranked as more unstable by all algorithms, indicating a regulation by Agac toxins." (PMID 29116140, 2017).
psoriasis (1 paper, 2021). An autoimmune condition characterized by red, well-delineated plaques with silvery scales that are usually on the extensor surfaces and scalp. "Inhibiting the expression of RPL22 can improve the clinical and pathological manifestations of IMQ-induced psoriasis mouse models, and overexpression of RPL22 can significantly promote psoriasis progression." (PMID 34220863, 2021). "Furtherly, we used ChIP-qPCR technology to detect the histone H3K27 acetylation level in the RPL22 promoter region in psoriasis lesions and found there were indeed hyperacetylated modification in the upstream of RPL22 sequence." (PMID 34220863, 2021). "We showed that RPL22 expression was significantly increased in the skin lesions of psoriasis patients and IMQ-treated psoriatic-like mice." (PMID 34220863, 2021). "In IMQ induced psoriasis-like mouse skins, RPL22 overexpression accelerating the development of psoriasis." (PMID 34220863, 2021). "RT-qPCR and WB showed that RPL22 expression was upregulated in lesional skins from psoriasis patients compared with healthy controls." (PMID 34220863, 2021). "But the exact regulation mechanisms of the acetylation level in the RPL22 promoter region in psoriasis lesions is unclear, which requires further study." (PMID 34220863, 2021). "Therefore, RPL22 can aggravate the progression of psoriasis by inducing abnormal biological behaviors of keratinocytes which is expected to become a novel therapeutic target in the future." (PMID 34220863, 2021). "To explore the critical role of RPL22 upregulation in the development of psoriasis in vivo, we established IMQ induced psoriasis-like mouse model and simultaneously injected with OE-RPL22 or si-RPL22 intradermally daily for the first three consecutive days (0/1/2/3 day)." (PMID 34220863, 2021). "Here, we believe that RPL22 plays a destructive role in psoriasis." (PMID 34220863, 2021). "In order to further explain the specific mechanism of the increased expression of RPL22 in psoriasis lesions, we predicted that there were H3K27 acetylated islands in the upstream promoter region of RPL22 through the UCSC Genome Browser, suggesting that this region might have active enhancers." (PMID 34220863, 2021). "Thus, RPL22 might be a novel potential molecular target for treatment of psoriasis." (PMID 34220863, 2021). "However, the aberrant expression and upstream regulatory mechanisms of the RPL22 gene in psoriatic lesions, as well as the importance in the pathogenesis of psoriasis, have not been reported." (PMID 34220863, 2021).
Sepsis (1 paper, 2022). Sepsis is defined as life-threatening organ dysfunction caused by a dysregulated host response to infection. "In summary, CD81, RPL22, GYPE, and HSPB1 were screened and they are significantly associated with the immunity in sepsis-induced ARDS." (PMID 34898369, 2022). "It was also found that CD81 and RPL22 in the green module were specific to sepsis-induced ARDS, and both of them were less expressed compared with the control group." (PMID 34898369, 2022).
viral infection (1 paper, 2024). "The interaction between eL22/RPL22 and EBER-1 has been shown to prevent the inhibition of PKR during viral infection." (PMID 39766272, 2024).
cancer (35 papers, 2017 to 2025). A tumor composed of atypical neoplastic, often pleomorphic cells that invade other tissues. "These cancers often display the point-mutated allele RPL22 p.K15fs, explained by the fact that RPL22 has vulnerable coding mononucleotide repeats." (PMID 40427096, 2025). "While RPL22 is mutated in cancer and clearly implicated in MDM4 splicing, what is the evidence regarding RPL5 and RPL11 in cancer?" (PMID 40427096, 2025). "Another RP, RPL22, is frequently mutated in cancers with microsatellite instability and its paralog RPL22L1 is often amplified." (PMID 40427096, 2025). "RPL22 point mutations are especially prevalent in cancers classified as microsatellite instability-high (MSI-H)." (PMID 40427096, 2025). "Loss of Rpl22 in mice activates the stress-induced NF-κB pathway, increasing expression of the stemness factor Lin28B, which then leads to cancer." (PMID 32432546, 2020). "The examination of detailed RPL22/eL22 mutations in the top four RPL22/eL22 mutated cancers revealed that the most frequent mutation—K15R frame shift accounts for 79.77% of all the mutations." (PMID 29207594, 2017). "Furthermore, reduced expression of RPL22 was associated with increased proliferation of cancer cells, and resistance to Nutlin-3a, an MDM2 inhibitor." (PMID 40427096, 2025). "Other dMMR/MSI‐associated immune escape mutations that varied in frequency between cancer types included RPL22, which was enriched in EC, and the antigen processing and presentation pathway components B2M, NLRC5, TAP2, and HLA‐B, which were more commonly disrupted in CRC." (PMID 35262923, 2022). "Genomic sequencing analysis of multiple types of human cancers revealed that the gene encoding the large subunit ribosome protein L22 (RPL22/eL22, all ribosome proteins will be named according to both old and new systems described in a review paper) is highly mutated in endometrial carcinoma." (PMID 29207594, 2017). "RPL22/eL22 is highly mutated in several cancer types and a pool of cancer cell lines." (PMID 29207594, 2017). "Interestingly, inactivation or loss of RPL22 in cancer is associated with increased expression of RPL22L1 and inclusion of exon 6 in MDM4, an event that promotes MDM4 expression by preventing formation of a ‘short’ MDM4 mRNA isoform (MDM4s) that is destroyed by nonsense-mediated decay." (PMID 38682900, 2024). "Recurrent mutations in genes of the large 60S subunit components RPL5, RPL10, RPL11, RPL22, and RPL23A, and the small 40S subunit components RPS15, RPS20, and RPS27 have been specifically implicated in cancer." (PMID 40805230, 2025). "Collectively, these studies establish RPL22 as a novel regulator of MDM4 with possible future implications for cancer prognosis and therapy." (PMID 40427096, 2025). "Somatic mutations and deletions affecting RPs, such as RPL5, RPL10, RPL22, and RPS15, have been identified across multiple cancer types." (PMID 40427096, 2025). "Ribosomal protein RPL22L1 is a homologous analogue of RPL22 that plays pivotal roles in a variety of human cancers." (PMID 39509434, 2024).
cancer (continued). "In this study, only RPL22 was verified as a potential downstream oncogene/translocated cancer gene of Drp1 in the ‘ribosome pathway’ using ENCORI Starbase." (PMID 35230214, 2022). "Mutations in RPL22 occur at an A8 homopolymer and have been detected in 51/148 MSI ECs (35%, TCGA pan-cancer cBioportal analysis), as well as 12/23 (52%) MSI ECs and 17/34 MSI EC." (PMID 35012638, 2022). "As the components of ribosome, Rps15a, Rps19, Rpl14, Rpl22 were preciously controlled by Myc and highly expressed in cancer cells, which promoted the EMT process." (PMID 34955855, 2021). "In prior reports, RPL22 was shown to control TGF-βpathway activation, with TGF-β signaling being closely linked to cancer progression and metastasis." (PMID 34178640, 2021). "Rpl22 has been recently shown to directly bind and block MDM2, which is intriguing, given the occurrence of inactivating mutations of RPL22 in various cancers." (PMID 29304067, 2018). "RPL22 was found to be significantly mutated in UCEC, according to a TCGA pan-cancer analysis." (PMID 28147343, 2017). "Perhaps local export of EBER1 from the EBV-infected cancer cells is sufficient to bind RPL22 in adjacent cytotoxic αβ T cells that are present in the lymphocytic infiltrate and consequently prevent survival or function of these T cells, contributing to immune evasion by the cancer." (PMID 41218767, 2025). "Inflammation is an established driver of many cancers including those of the liver and NF-κB has been shown to promote HCC in the setting of cholestatic-induced liver injury akin to that seen in ΔS6 livers as well as in the setting of Rpl22-deficiency via induction of the pluripotency factor Lin28b." (PMID 36656901, 2023). "Among 6 up-regulated cancer driver genes, 4 genes encode proteins known to function as negative regulators of cell proliferation (CDKN2A); inducers of apoptosis (BAX); tumor suppressor (RPL22); inhibitors of transactivation of insulin promoter by recruiting a repressor complex (SPOP)." (PMID 36879662, 2022). "Specific missense mutation matches have been found to six proteins from the COSMIC Cancer Gene Census database (FLNA, RPL22, SDHA, NFATC2, NPM1, and CLTCL1)." (PMID 31316139, 2019).
cancer (continued). "RPL22 and its paralog RPL22L1 (RPL22 Like-1) provide an interesting example of compensation, and in this case, it also extends beyond translation to influence cancer-related signaling pathways." (PMID 40427096, 2025). "Our analyses did not pick up RPL22, RPS27 (eS27), RPS15 and RPL10, although already described in cancer as well." (PMID 28147343, 2017). "Our findings that the N- and C-termini of RPL22/eL22 play distinct roles in MDM2 inhibition may also explain why most of the RPL22/eL22 mutations are deletion mutations, as otherwise the inhibitory effect on MDM2 by different domains of RPL22/eL22 may not be eliminated completely in cancer cells." (PMID 29207594, 2017). "However, protein expression of RPL22 did not change in Mdivi-1-exposed SGC7901 and BGC823 cancer cells." (PMID 35230214, 2022). "Since RPL22/eL22 is not an essential ribosome protein for protein translation and cell growth, these data suggest a potential tumor suppression role of RPL22/eL22 in human cancers." (PMID 29207594, 2017).